MUC2 (mucin 2, oligomeric mucus/gel-forming)
Diseases named in the same sentence as MUC2 in open-access papers (continued):
Sharing a sentence is not in itself a finding about the gene and the disease.
adenocarcinoma (36 papers, 2004 to 2024). A common cancer characterized by the presence of malignant glandular cells. "Meanwhile, increased expression of mucins, especially MUC-2, in the bronchial epithelium is associated with adenocarcinoma and can be used as an oncological marker." (PMID 36648870, 2022). "In adenocarcinoma, MUC2 expression inversely correlates to disease severity, and reduced MUC2 is associated with advanced stages of disease." (PMID 29414601, 2018). "The main difference between adenocarcinoma of the pancreas and IPMT is an increased expression of MUC2 associated with a decreased expression of MUC1 in IPMT vs adenocarcinoma." (PMID 15494719, 2004). "Regarding intestinal differentiation, we confirmed the reduced expression of MUC2 protein in adenocarcinoma tissue." (PMID 39337548, 2024). "Immunohistochemical staining demonstrated statistical significance (p < 0.01) only for the strong intensity of the MUC2 antigen in the adenocarcinoma tissue of the colon." (PMID 39337548, 2024). "The 0-IIa lesion was composed of a tubular structure positive for MUC2, and it was diagnosed as an intestinal phenotype of well differentiated adenocarcinoma." (PMID 28591047, 2017). "qRT-PCR indicated that expression of MUC2 and VILLIN, enterocyte-like cell differentiation markers associated with axial microfilaments and conserved in adenocarcinoma, decreased, whereas expression of PPARY increased." (PMID 25970424, 2015). "Immunohistochemistry demonstrated a positive MUC2 expression compatible with an intestinal type Adenocarcinoma." (PMID 19272137, 2009). "Consistent with the clinicopathological feature of excess mucin production, the IHS scoring revealed that MUC-2 expression was increased in PMP tissue compared with adenocarcinoma (P<0.001)." (PMID 17031402, 2006). "MUC2 has a reduced amount of antigen-positive cells in the adenocarcinoma tissue of the colon." (PMID 39337548, 2024). "β-catenin and MUC2 showed inverse expression in the adenocarcinoma tissue of CRC." (PMID 39337548, 2024). "To determine whether the observed oligomerization state was specific to HEK293F cells, we transfected the MUC2D3 plasmid and the plasmid containing the entire amino-terminal region of MUC2 into cells of the Caco-2 line (epithelial colon-derived adenocarcinoma)." (PMID 31310764, 2019). "A total of four studies looked specifically at the adenocarcinoma of the oesophago-gastric junction (GOJc), analysing MUC1, MUC2, MUC5AC and MUC6 in 191 surgically resected specimens." (PMID 37958425, 2023). "Intestinal-type adenocarcinomas generally express CDX-2, MUC2 and CD10, whereas the gastric-type adenocarcinomas express MUC5AC and MUC6." (PMID 35565398, 2022). "Panels of immunohistochemistry including MUC1, MUC2, CDX2, CK20 and MUC5AC can help in the classification of adenocarcinomas as intestinal or pancreatobiliary type in a substantial proportion of cases." (PMID 35565398, 2022). "Here, we sought to characterize the expression profile of SOX2 and CDX2 in the sequential alterations of the esophageal mucosa towards adenocarcinoma and compare it with the well-established gastric and intestinal mucin profiles (MUC5AC, MUC6, and MUC2)." (PMID 27766003, 2016). "Based on this background information, this study investigated the pattern of expression of MUC2 and MUC5AC mucin gene protein products using immunohistochemistry in patients with adenocarcinoma arising in BE." (PMID 19272137, 2009). "As in other studies, we demonstrated increased expression of MUC-2 in PMP tissue compared with normal mucosa and adenocarcinoma." (PMID 17031402, 2006). "Interleukin-9, which induces MUC-2 and MUC-5AC gene expression in the lung, and its receptor, IL-9Rα, were expressed at variable levels in all cases of PMP with increased IL-9 expression in the epithelial PMP cells compared with adenocarcinoma." (PMID 17031402, 2006). "MUC2 and MUC5AC levels were shown to be very high in IPMT compared to adenocarcinomas." (PMID 15494719, 2004).
adenocarcinoma (continued). "As it was shown previously, ITAC and adenocarcinomas of the intestinal tract show to a great extent morphological similarities, as well as overlapping immunohistochemical expression profile, including typically positive staining for CK20, CDX2, villin, MUC2 and SATB2." (PMID 35015192, 2022). "The 0-IIa lesion was positive for MUC2 and negative for MUC5AC, and thus the tumor cells of 0-IIa were deemed intestinal phenotype of well differentiated adenocarcinoma." (PMID 28591047, 2017). "Adenocarcinomas of the breast usually express MUC1 but not MUC2, whereas gastrointestinal adenocarcinomas frequently express MUC2 but less frequently express MUC1." (PMID 23938020, 2013). "Our results showed that more than 90% of cases diagnosed as primary adenocarcinoma of the gallbladder were positive for CK7 (97.6%), CK19 (98.2%), CKLMW (100%), CKHMW (91.6%), or MUC1 (97.1%) expression, or were negative for vimentin (96.1%) or MUC2 (96.9%)." (PMID 33494186, 2021).
inflammation (22 papers, 2015 to 2026). Aberrant reaction of the microcirculation characterized by movement of fluid and leukocytes from the blood into extravascular tissues. "Knockdown of ZO-1, occludin, or MUC2 in mice impairs intestinal mucosal repair and increases the risk of intestinal inflammation." (PMID 39717557, 2024). "In the Winnie model, spontaneous chronic intestinal inflammation arises as a consequence of a missense mutation in MUC2 gene, which leads to MUC2 protein misfolding and significantly decreased mucin biosynthesis." (PMID 32998266, 2020). "This study evaluated the impact of idebenone in Winnie mice, that are characterized by spontaneous chronic intestinal inflammation and ER stress caused by a missense mutation in the mucin MUC2 gene." (PMID 32998266, 2020). "Animal studies demonstrated that MUC2-deficient mice have chronic colonic inflammation, and dextran sulfate sodium-induced chronic intestinal inflammation has mucus barrier damage in mice colon." (PMID 29599128, 2018). "O-glycosylation of mucin MUC2 is implicated in colonic inflammation in UC." (PMID 38886669, 2024). "Of note, this finding resembles a finding in Muc2 -/- mice, which develop spontaneous low-grade intestinal inflammation, and also display lower glucose levels." (PMID 39620359, 2024). "In the present study, we demonstrated that the transcript levels for muc1, muc2, muc3, muc4, muc5b and muc13 in lung tissue were unaltered, whereas muc5ac transcript expression was significantly increased during allergen-induced airway inflammation in mice." (PMID 28205598, 2017). "Absence of APN is protective against DSS-induced acute colonic inflammation by means of reducing colon tissue-secreted pro-inflammatory cytokines, modulating goblet and epithelial cell expressions, and increasing the levels of secretory mucin MUC2." (PMID 25949213, 2015). "The individual mucins were investigated for different reasons: MUC2—the main secreted mucin—and MUC13—the main transmembrane mucins—are essential for the integrity of the intestinal mucus barrier; a distortion of their expression increases the susceptibility to develop intestinal inflammations." (PMID 34685068, 2021). "Misfolding of MUC2 protein due to reduced biosynthesis and secretion triggers aberrant ER stress, activation of the unfolded protein response (UPR) and spontaneous chronic intestinal inflammation in Winnie mice." (PMID 32998266, 2020). "On a transcriptional level, Muc2 mRNA expression was reduced in steady-state Nr2f6−/− colon specimens, although not significantly, but a strongly reduced Muc2 mRNA expression level in Nr2f6−/− colons was observed on day 7 on DSS treatment-induced intestinal inflammation." (PMID 28779026, 2018). "Thus, in GI inflammation, a dysfunctional epithelial barrier could be ascribed to the high mucus biosynthesis and goblet cell apoptosis, which aligns with our finding that depleting of NE by DSP-4 accelerates the biosynthesis and secretion of MUC2 in the large intestine." (PMID 36845109, 2023).
intestinal diseases (18 papers, 2017 to 2025). "Studies have shown that the loss of MUC2 expression in the intestinal mucosa can lead to intestinal diseases such as bacterial diarrhoea." (PMID 39859316, 2025). "MUC2 is secreted by goblet cells, which constitute the structural backbone of the intestinal epithelial mucus layer, and the abnormal expression of MUC2 is closely associated with the occurrence of intestinal diseases." (PMID 38672341, 2024). "By identifying genetic markers associated with MUC2 expression, pigs with stronger intestinal immune function could be bred to better cope with weaning stress and intestinal diseases." (PMID 39859316, 2025). "Moreover, we demonstrated that NZ-IL36γ increased the abundances of Acetatifactor, Eubacterium, Monoglobus, and Roseburia species in the mouse intestine, and that they were associated with Muc2 expression and possibly with the prevention of intestinal diseases." (PMID 39446273, 2024). "Another essential target to avoid intestinal diseases is the mucus layer, with goblet cells being the specialized intestinal cells involved in the production and release of mucins, mostly MUC2." (PMID 38315242, 2024). "Mucin-2 (MUC2) is a core component of mucus and the best-studied mucus protein, and its dysregulated production is related to various intestinal diseases." (PMID 38392196, 2024). "Muc2 is regarded as a marker of colorectal carcinoma, and there is a lot of research about its effects on intestinal diseases." (PMID 36010498, 2022). "MUC2 and TFF3 expression undergo changes during intestinal diseases caused by pathogenic bacteria, for instance." (PMID 34183045, 2021). "Therefore, we would like to review the characteristics of MUC2 and its role in intestinal disorders and highlight the importance of further studies." (PMID 35602503, 2022). "In this study, we aimed to build on the known role of MUC2 and TFF3 in intestinal bacterial infections and to identify novel regulatory aspects." (PMID 34183045, 2021).
bacterial infection (17 papers, 2010 to 2025). "Abnormalities in mucous layers, underproduction of Muc2 by goblet cells and mutated Muc2 results in elevated risk for bacterial infection." (PMID 31540475, 2019). "To assess the role of Muc2 during A/E bacterial infections, we inoculated Muc2 deficient (Muc2−/−) mice with Citrobacter rodentium, a murine A/E pathogen related to diarrheagenic A/E E. coli." (PMID 20485566, 2010). "Decreased MUC2 expression, as observed in some bacterial infections, can compromise mucosal integrity." (PMID 39794952, 2024). "Previous studies have found that Muc2 synthesis is essential for host protection during A/E bacterial infection because it reduces the overall number of pathogens and symbionts associated with the colonic mucosal surface." (PMID 36145206, 2022). "The relationship between bacterial infection and over expression of MUC2 and MUC5AC were emphasized especially in the respiratory tract and middle ear epithelial cells." (PMID 22073249, 2011). "In conclusion, Muc2 production is critical for host protection during A/E bacterial infections, by limiting overall pathogen and commensal numbers associated with the colonic mucosal surface." (PMID 20485566, 2010). "Additionally, B. licheniformis was found to upregulate intestinal MUC-2 expression in chickens and pigs, emphasizing its role in fortifying the mucus layer as a chemical barrier against bacterial infections." (PMID 37760314, 2023). "Muc2 production is clearly protective during A/E bacterial infection, but whether this is true for other enteric bacterial pathogens of the gut remains to be shown." (PMID 20485566, 2010). "With the increased expression of MUC-2 after diet, Butyrate seems to have stimulated MUC-2 secretion to restore the barrier function against bacterial infection in the gut." (PMID 35008767, 2021). "Mucin-2 (MUC-2) constitutes a pivotal component of the mucus layer covering the intestinal epithelium and thereby combats bacterial infections and maintains epithelial barrier integrity." (PMID 28127403, 2017). "It shows that in the intestine bacterial infection potentiate more severe pathology in the absence of secreted mucin MUC2." (PMID 25365201, 2014). "Indeed, production of the anti-microbial effector inducible nitric oxide synthase (iNOS), which is induced in myeloid cells upon sensing luminal bacterial infection, was also induced in myeloid cells in the MLN of some Muc2−/− mice." (PMID 24945909, 2014).
colon (11 papers, 2013 to 2025). "Similarly, mucinous differentiation of gastrointestinal tumors, in particular increased or de novo expression of MUC2 and/or MUC5AC, is widely believed to imply an adverse clinicopathological feature." (PMID 26436698, 2015). "However, prior studies have not firmly established whether this was due to acquisition of MUC2 expression by non-gastrointestinal tumor cells and/or cells with an intestinal lineage origin." (PMID 40018643, 2025). "As the principal gastrointestinal mucins capable of forming viscous gels, MUC2 and MUC5AC can similarly play important roles in the pathogenesis and resilience of other mucin-secreting gastrointestinal tumors." (PMID 26436698, 2015). "Through formation of viscous gels, too, MUC2 and MUC5AC significantly contribute to the biology and pathogenesis of mucin-secreting gastrointestinal tumors." (PMID 26436698, 2015).
gastrointestinal disease (6 papers, 2018 to 2022). A disease that occurs in the gastrointestinal system, excluding the hepatobiliary system. "Mucin 2 (MUC-2) is the first described intestinal mucin gene; abnormalities in its expression indicate the occurrence of some gastrointestinal diseases, and the decreased expression of MUC-2 indicates higher tissue damage." (PMID 32244599, 2020).
metabolic disorders (4 papers, 2024 to 2025). "As a novel biotherapeutic agent, Akkermansia can induce the expression of mucins MUC2 and MUC3, thereby preventing the adhesion of enteropathogenic Escherichia coli (EPEC) to the epithelium and improving health by regulating various metabolic disorders." (PMID 40298780, 2025).
infectious disease (2 papers, 2010 to 2024). A disorder directly resulting from the presence and activity of a microbial, viral, or parasitic agent in humans. "Since Muc2 is an integral part of the colonic ecosystem, future studies are warranted to unravel precisely how intestinal mucus impacts the course of infectious disease." (PMID 20485566, 2010).
respiratory disease (2 papers, 2022 to 2023). "Therefore, reducing MUC5AC and MUC2 expression may effectively alleviate excessive mucus production in respiratory diseases." (PMID 37687271, 2023). "Type II gastric mucin contains mucin 2 and mucin 6 (MUC2/MUC6), as well MUC5AC, and although these are not the major secreted mucins in saliva, they are gel-forming and serve as a surrogate for the secretory gel-forming mucins in saliva upregulated during respiratory disease." (PMID 36146663, 2022).
benign tumor (1 paper, 2013). "The results demonstrated “+” MUC2-immunostaining in 36.4% of the benign cases, and no benign tumor cases with higher immunostaining levels were detected." (PMID 24324582, 2013).
MUC2 also shares sentences with these, for which no sentence is quoted: chronic bronchitis (4 papers); gastrointestinal disorders (4); colorectal (3); type 2 diabetes (3); adenocarcinoma of the urinary bladder (2); bacteremia (2); brain cancer (2); chronic gastritis (2); meningioma (2); pancreatic adenocarcinoma (2); pancreatitis (2); abscesses (1); acute kidney injury (1); Airway obstruction (1); ampulla of Vater (1); appendiceal neoplasm (1); Arthritis (1); Atrophy (1); autism (1); benign ovarian tumor (1); brain tumors (1); bronchioalveolar carcinoma (1); cardiovascular diseases (1); cholelithiasis (1); cholera (1); chronic pancreatitis (1); Cirrhosis (1); Cognitive impairment (1); colon disorders (1); diverticulosis (1).
A further 38 diseases each share a sentence with MUC2 in 1 paper.